PLD2 (phospholipase D2)
Diseases named in the same sentence as PLD2 in open-access papers (continued):
Sharing a sentence is not in itself a finding about the gene and the disease.
Alzheimer disease (7 papers, 2010 to 2023). A progressive, neurodegenerative disease characterized by loss of function and death of nerve cells in several areas of the brain leading to loss of cognitive function such as memory and language. "Among the upregulated DDEGs in SGNs, Sncb encodes a member of a small family of proteins that inhibit phospholipase D2, which is abundant in neurofibrillary lesions of patients with Alzheimer’s disease and has been reported to trigger oxidative stress and inflammatory responses in the aged retina." (PMID 36933008, 2023). "The PLD2 knock out (PLD2KO) mouse has been previously reported to be protected from insult in a model of Alzheimer's disease." (PMID 27658289, 2016). "Synuclein selectively inhibits phospholipase D2 and is abundant in neurofibrillary lesions of patients with Alzheimer's disease." (PMID 21118505, 2010). "Similarly, both PLD1 and PLD2 reportedly regulate macrophage phagocytosis, Alzheimer’s disease, and tumor growth." (PMID 32971863, 2020). "However, different roles of PLD1 and PLD2 in Alzheimer Disease have been found." (PMID 28219337, 2017). "SNCB, known for its role in Alzheimer’s disease, was decreased in GBM tissue 4-fold compared to peritumoural-control tissue and inhibits phospholipase D2 (PLD2) which is oncogenic." (PMID 24728830, 2014).
glioblastoma (7 papers, 2014 to 2024). The most malignant astrocytic tumor (WHO grade IV). "This study demonstrated, for the first time, that the inhibition of PLD2 activity and the following Akt behavior lead to the decline of glioblastoma cell viability through the inhibition of the autophagic flux." (PMID 37238668, 2023). "Among various considerations, it has been evidenced PLD2 as a key regulator of pro-survival RAC(Rho family)-alpha serine/threonine-protein kinase (Akt) in glioblastoma." (PMID 37238668, 2023). "For instance, Transfection of miR-203 mimetics into U251 glioblastoma cells, which showed a decrease in miR-203 levels relative to less malignant gliomas or normal gliomas, led to inhibition of the PLD2 (phospholipase D2) oncogene, the target of miR-203." (PMID 35846075, 2022). "The data were similar to the findings in glioblastoma and prostate cancer, in which miR-203 was down-regulated, and ectopic expression of miR-203 suppressed cell proliferation and induced a G1-phase arrest by targeting PLD2." (PMID 25373785, 2014). "Subsequently, experiments carried out employing human glioblastoma cells revealed that CK2 interacts with both PLD1 and PLD2, and that the CK2-mediated phosphorylation of PLD2 leads to its activation." (PMID 33027921, 2020). "The human cerebrum, astrocytes, neuronal progenitor cells, NTera2 teratocarcinoma-derived neurons, SK-N-SH neuroblastoma, IMR-32 neuroblastoma, U-373MG glioblastoma, T98 glioblastoma, and HMO6 immortalized microglia constitutively expressed PLD1, PLD2, and PLD3 transcripts (lanes 1, 3 to 10)." (PMID 25478031, 2014). "Importantly, treatment with CTR-GNPs significantly decreased the levels of metalloproteinase (MMP)-2/-9 and phospholipase D1 (PLD1) and protein but not PLD2, which is involved in the modulation of migration and the invasion of glioblastoma cells." (PMID 32074974, 2020).
Sepsis (7 papers, 2016 to 2025). Sepsis is defined as life-threatening organ dysfunction caused by a dysregulated host response to infection. "Gene microarray analysis of whole blood samples collected from individuals with sepsis revealed a notable positive association between the expression level of PLD2 and the rate of mortality observed in these patients." (PMID 38630134, 2024). "Reportedly, PLD2 deficient sepsis mice exhibit notable characteristics, including improved survival, decreased organ damage, and increased neutrophil number in lung tissue." (PMID 37249288, 2023). "In experimental sepsis model, PLD2 deficiency protects wild-type mice against sepsis-induced death by enhancing neutrophil recruitment." (PMID 27721573, 2016). "A CXCR2-selective antagonist (SB225002) abolishes the protection conferred by PLD2 deficiency during experimental sepsis, suggesting that enhanced CXCR2 expression in neutrophils promotes survival in PLD2−/− mice." (PMID 27721573, 2016). "SICM is associated with a worse prognosis in sepsis, and PLD2 may decrease survival in patients with sepsis by exacerbating myocardial injury." (PMID 38630134, 2024). "Finally, better outcomes in sepsis were reported by Lee and coworkers in mice deficient for phospholipase D2 (PLD2) that exhibit an intrinsic up-regulation of PAD4 activity associated with augmenting NET formation and bacterial killing." (PMID 35967320, 2022). "In sepsis, PLD2 deficiency increased survival of mice and diminished organ damage during sepsis." (PMID 29968773, 2018). "Phospholipase D2 (PLD2) is crucial in mediating inflammatory reactions and is associated with the prognosis of patients with sepsis." (PMID 38630134, 2024). "Our previous study highlighted the role of neutrophil PLD2 in the pathogenesis of sepsis; pharmacological targeting of PLD2 effectively prevented the progression of sepsis by enhancing the recruitment of neutrophils." (PMID 28484281, 2017). "Evidence has shown that PLD2 participates in the pathogenesis of several diseases, such as pathological angiogenesis, sepsis, asthma, Alzheimer's disease, and cancer." (PMID 27721573, 2016). "In addition, phospholipase D2 (PLD2) deletion ameliorates sepsis-induced cardiomyopathy by suppressing cardiomyocyte pyroptosis via the NLRP3/caspase-1/GSDMD pathway." (PMID 40708650, 2025). "Our previous study also demonstrated that PLD2 knockdown improved survival in mice with sepsis." (PMID 38630134, 2024). "Our previous studies demonstrated that PLD2 knockout improved the survival of mice with sepsis." (PMID 38630134, 2024). "Previous work has demonstrated that PLD2 participates in the pathogenesis of sepsis and chronic asthma; we hypothesized that PLD2 may also involve the induction and development of IBD." (PMID 27721573, 2016). "Moreover, PLD2 also induces the aggravation and drives mortality in sepsis by inhibiting the formation of neutrophil extracellular trap and reducing the expression of CXCR2." (PMID 27721573, 2016).
colon cancer (6 papers, 2009 to 2024). "Here we show that the OC cell lines ES-2, SKOV3 and OVCAR8 under hypoxia show upregulated expression of PLD2, which encodes phospholipase D2, in these cells in a Hif-1α-dependent manner, as recently reported in colon cancer." (PMID 38403587, 2024). "cPA intracellularly produced by PLD2 suppresses PPARγ8 and inhibits intimal thickening and proliferation of colon cancer cells by inducing apoptosis." (PMID 37193762, 2023). "Experimental results indicate that phospholipase D2 (PLD2) is overexpressed in colon tumors and is secreted by cancer cells to induce senescence in neighboring fibroblasts." (PMID 35836256, 2022). "Studies showed that overexpressed PLD2 is secreted by colon tumor cells and changes the microenvironment to increase stem cell fate of tumor cells by inducing senescence in neighboring fibroblasts, which demonstrates the importance of secretion in PLD2 function." (PMID 34879072, 2021). "In colon cancer cells Rac signaling to PAK controls PKC/fascin interactions to regulate their migration, and spingosine1P signaling to PKCε subsequently activates a PLD2-PKCζ-Rac1 cascade to stimulate migration of endothelial cells." (PMID 19400942, 2009). "Inhibition of PLD2 could promote colon cancer cell apoptosis through downregulating PI3K-AKT signaling pathway and play a protective role in colonic cancer." (PMID 27721573, 2016).
glioma (5 papers, 2008 to 2024). A benign or malignant brain and spinal cord tumor that arises from glial cells (astrocytes, oligodendrocytes, ependymal cells). "As to glioma, shattered reports showed that PLD1 and its isoform PLD2 were upregulated in cell lines of glioma associating with increased capacities of invasion and migration." (PMID 28915652, 2017). "Four genes have clearly identified functions in the central nervous system: APPA4 functions in Notch signaling during neural development, cell adhesion and apoptosis; RTN4 is a neurite growth inhibitor; and SNCB, which is upregulated in glial tumors, is thought to regulate phospholipase D2 activity." (PMID 18474104, 2008). "The activation of HIF-1α expression or activity by PLD2 has been reported in endothelial, glioma and renal cancer cells, but there is evidence of the opposite effect in HEK293 cells, suggesting that this feedback loop may work in specific contexts or cell types." (PMID 38403587, 2024). "Consistently, in glioma cells, the overexpression of PLD-1 and PLD-2 enhanced the expression of antiapoptotic genes." (PMID 25489735, 2014).
breast tumors (4 papers, 2014 to 2022). "PLD2 is a key factor for cell invasion that contributes critically to growth and metastasis of breast tumors in vivo, which have clear pharmacological implications in humans." (PMID 24103483, 2014). "Data from this current study indicates that primary breast tumors increased in both tumor volume and metastases as a function of time and that PLD-specific inhibitors decreased both of these factors, which strongly suggests PLD2 has a role in breast tumor progression." (PMID 27851813, 2016). "In preclinical studies, PLD inhibitors [FIPI (dual PLD1/PLD2 inhibitor) or VU0155072-2 (PLD2 inhibitor)] were found to reduce the tumor-promoting macrophages and neutrophil infiltration in primary breast tumors and liver metastasis, thereby suppressing BCLM." (PMID 36387238, 2022).
colitis (4 papers, 2016 to 2025). Inflammation of the colon. "We found that knocking out Pld2 in intestinal epithelium alleviated the symptoms of colitis in mice." (PMID 28484281, 2017). "We demonstrate that genetic ablation of intestinal epithelial PLD2 prevents DSS-treated mice from developing colitis by improving the intestinal integrity." (PMID 28484281, 2017). "We have generated intestinal-specific Pld2 knockout mice (Pld2 IEC-KO) to investigate the mechanism of intestinal epithelial PLD2 in colitis." (PMID 28484281, 2017). "We show that the knockout of Pld2 confers protection against dextran sodium sulphate (DSS)-induced colitis in mice." (PMID 28484281, 2017). "In this study, we show that the genetic or pharmacological inhibition of PLD2 restored occludin levels, alleviated the symptoms of colitis, and improved the survival rate of the mice." (PMID 28484281, 2017). "To investigate the changes in the expression of PLD2 in the pathogenesis of colitis, we orally fed C57BL/6 mice with 2% DSS for 7 days and analysed PLD2 expression in whole intestinal lysates." (PMID 28484281, 2017). "PLD2 IEC-KO mice showed less severe symptoms of colitis after intrarectal administration of 200 mg/kg of DNBS in 35% ethanol." (PMID 28484281, 2017). "Our results suggest that intestinal epithelial-specific PLD2 mediates the disease progression in DSS-induced colitis." (PMID 28484281, 2017). "Our results show that IEC-KO mice had less severe symptoms of colitis, indicating a protective role of PLD2 in the hapten-induced colitis model." (PMID 28484281, 2017). "PLD2 selective inhibitor (CAY10594) was administrated daily by oral gavage in DSS-induced colitis mice." (PMID 27721573, 2016). "Furthermore, treatment of mice with dextran sodium sulfate (DSS), a chemical agent that induces colitis, downregulates expression of occludin, a tight junction protein, in intestinal epithelial cells (IECs) in a phospholipase D2 (PLD2)-mediated pathway." (PMID 39860613, 2025). "Although we focused on the epithelial-specific role of PLD2 in colitis, it is plausible that the protective effect, observed in the DSS-induced colitis in our in-vivo PLD2 inhibition study, is a cumulative effect of PLD2 ablation in both neutrophils and intestinal epithelial cells." (PMID 28484281, 2017). "Thus, we show that PLD2 plays a role in the pathology of experimental colitis by influencing the maintenance of epithelial barrier integrity in the intestinal epithelial cells." (PMID 28484281, 2017). "Additionally, we have shown that treatment with an inhibitor of PLD2 can rescue mice from DSS-induced colitis." (PMID 28484281, 2017). "In this study, we found that blockade of PLD2 with selective inhibitor could ameliorate DSS-induced colitis in mice and promote neutrophil mobilization from the bone marrow into intestinal mucosa." (PMID 27721573, 2016). "Hence, we used a DNBS-induced colitis model to evaluate whether PLD2 affects other experimental colitis models." (PMID 28484281, 2017). "To validate the effect of PLD2 inhibition on the development of colitis, we co-treated wild type mice with DSS and 10 mg/kg of VU0364739.HCl, which is a chemical inhibitor of Pld2; we then monitored the clinical phenotype of DSS-induced colitis." (PMID 28484281, 2017). "To examine the mechanism of intestinal epithelial PLD2 in DSS-induced colitis, we generated intestine-specific Pld2 knockout (Pld2 IEC KO) mice by mating Pld2 floxed mice with Villin-Cre mice." (PMID 28484281, 2017). "Increased expression of PLD2 was found in mouse neutrophils, after treatment with DSS, and in neutrophils from patients with colitis." (PMID 28484281, 2017). "Control mice had significantly lower survival rate compared to Pld2 IEC KO mice, which suggests that intestine-specific ablation of Pld2 plays a protective role in DSS-induced colitis." (PMID 28484281, 2017). "To determine how PLD2 regulated intestinal mucosal inflammation, we isolated bone marrow cells from mice with DSS-induced colitis." (PMID 27721573, 2016).
colitis (continued). "To further determine the role of PLD2, we isolated neutrophils from bone marrow of wild-type mice with DSS-induced colitis and analyzed neutrophil migration in Transwell plate in vitro." (PMID 27721573, 2016). "This increase in PLD2, got us speculate that PLD2 might be playing a role in the pathogenesis of DSS-induced colitis." (PMID 28484281, 2017). "We investigated whether the protective role of PLD2 is specific to DSS-induced colitis, or is a general mechanism also active in other models as well as in colitis pathogenesis in humans." (PMID 28484281, 2017). "Next, we examined whether the protective role of intestinal PLD2 knockdown is limited to DSS-induced colitis, by using a dinitrobenzene sulphonic acid (DNBS)-induced colitis model." (PMID 28484281, 2017). "Recently, it was reported in an experimental colitis model that dextran sodium sulfate (DSS) treatment, a chemical agent known to induce colitis, elevated the c-Src-mediated tyrosine phosphorylation of occludin in a phospholipase D2 (PLD2)-mediated pathway in PLD2 knockout mice." (PMID 30115904, 2018).
Hypertension (4 papers, 2017 to 2023). The presence of chronic increased pressure in the systemic arterial system. "On the other hand, single nucleotide polymorphisms in PLD2 have been associated with several types of cancer and hypertension, suggesting that there are likely individual variations in the activity of this enzyme." (PMID 34445455, 2021). "Based on these studies, the report that a polymorphism in human PLD2 negatively correlates with the development of hypertension appeared to support the hypothesis that PLD2 promotes increased blood pressure and that loss of PLD2 function should result in hypotension." (PMID 28831159, 2017). "Studies showed that biomarkers include PLD2, FLNA (filamin A), SMURF1, LINGO1, CACNA1H, NLRP6, NLRC3, CXCR2 and C5AR1 plays an important role in progression of hypertension." (PMID 36837510, 2023). "Unexpectedly, we report here that mice lacking PLD2 exhibit hypertension as a consequence of reduced levels of eNOS, which accordingly decreases production of NO, an important physiological vasodilatory factor." (PMID 28831159, 2017).
lung carcinoma (4 papers, 2017 to 2021). "Several reports have focused on the PLD1/PLD2 balance and switch in different cancer types; however, there are few reports on lung cancer." (PMID 35127525, 2021). "We then recruited CAY10594 (specific for PLD2) treatment, which can significantly reduce the ELISA activity of PLD2 in lung cancer cells." (PMID 35127525, 2021). "We examined the expression levels of PLD1 and PLD2 in some lung cancer cell lines (A549 and H460) of the same cohort (GSE116436)." (PMID 35127525, 2021). "We currently speculate that PLD1 can dominate lung cancer metastasis and supplement the production of PA after the function of PLD2 is attenuated or even more, but this requires further research." (PMID 35127525, 2021). "To investigate whether the ALDOA/PLD1 axis has clinical significance for cancer patients, we performed the immunohistochemical (IHC) staining of ALDOA, PLD1, and PLD2 with specific antibodies in clinical lung cancer samples to validate these findings." (PMID 35127525, 2021). "Indeed, in our previous study, we observed that increased expression of PKCβII in lung cancer cells directly engaged the PLD2 pathway to hyperactive mTORC1." (PMID 28926616, 2017). "Therefore, we hypothesized that the ALDOA/PLD2 protein–protein interaction may be through the degradation mechanism of lung cancer cells." (PMID 35127525, 2021). "Therefore, we studied the role of PLD1/PLD2 in lung cancer and assessed whether enzyme activity and protein function are involved in lung cancer progression." (PMID 35127525, 2021). "In this study, we provide evidence that ALDOA directly binds to PLD2 to suppress its specific enzymatic activity, resulting in an increase in PLD1 levels and an increase in total PLD enzyme activity to promote lung cancer cell invasion." (PMID 35127525, 2021). "We first treated the lung cancer cell line A549 with alkylating drugs (cisplatin or temozolomide) to simulate the previous in silico dataset, then added PLD1/PLD2 inhibitors, respectively." (PMID 35127525, 2021).
lymphoma (4 papers, 2010 to 2021). A malignant (clonal) proliferation of B- lymphocytes or T- lymphocytes which involves the lymph nodes, bone marrow and/or extranodal sites. "Wild-type PLD2 was found to be increased in EL4 lymphoma metastasis in vivo, but an inactive form of PLD2 was associated with fewer liver metastases than those of control cells." (PMID 35127525, 2021). "PLD2’s lipase activity is implicated in migration and invasion of lymphoma cells via focal adhesion kinase (FAK) activation." (PMID 24103483, 2014). "Overexpression of lipase-active phospholipase D2 (PLD2) in lymphoma cells was found to be important for tumorigenesis of liver metastases to occur in vivo, while overexpression of enzymatically-inactive PLD2 hindered liver metastases." (PMID 27851813, 2016). "PLD2 enhances the expression of anti-apoptotic proteins, such as Bcl-2 and Bcl-xL in lymphoma cells." (PMID 24103483, 2014). "Taken together, the data suggest that PLD2 acts in concert with EGFR to enhance mitogenesis and invasion in lymphoma cells." (PMID 27713341, 2010). "This study has established that PLD2 up-regulates EGFR expression, as well as EGF-induced Akt activation, in a murine lymphoma cell line." (PMID 27713341, 2010).